BRCA1 (BRCA1 DNA repair associated)
Diseases named in the same sentence as BRCA1 in open-access papers (continued):
Sharing a sentence is not in itself a finding about the gene and the disease.
breast cancer (continued). "This study confirmed that patients diagnosed with invasive breast cancer aged 18–40 years have a high breast-cancer-specific mortality, and a high proportion are BRCA1 and BRCA2 mutation carriers." (PMID 29337092, 2018). "BRCA1-deficient breast cancer is an extensively studied hereditary cancer that exhibits significantly higher levels of chromosomal abnormality than sporadic breast cancers." (PMID 30327455, 2018). "Maximizing the therapeutic benefit of vinblastine treatment of BRCA1-associated mammary tumors would be facilitated by the ability to distinguish potential responders by analyzing the tumor at baseline (i.e., before initiation of treatment)." (PMID 30327455, 2018). "Prophylactic contralateral mastectomy has been shown to reduce the risk of death from breast cancer in BRCA1 and BRCA2 carriers by approximately 50%." (PMID 29266833, 2018). "Patients in the immediate reconstruction group significantly more often had a genetic predisposition to breast cancer (i.e., BRCA1, BRCA2, and/or CHEK2 mutations; p < 0.001) and a lumpectomy in their medical history (p = 0.032)." (PMID 29399731, 2018). "Additional studies will be required to realize the potential of this strategy and to confirm the utility of these markers for future clinical application with vinblastine treatment of BRCA1-associated breast cancer." (PMID 30327455, 2018). "Accordingly, association of plasma gelsolin levels with BRCA1 mutation status increased the sensitivity of this combined biomarker in early diagnosis of breast cancer." (PMID 30149613, 2018). "PARPi is used as a targeted therapy for treating breast cancer susceptibility gene 1/2 (BRCA1/2)-mutant tumors by causing S-phase-specific DNA damage, which these cells cannot cope with due to their homologous recombination (HR) repair deficiency." (PMID 30266942, 2018). "A similar phenotype was identified in breast cancer patients, with a significant number of BRCA1/2 somatic mutations (up to 20%) and somatic or germline mutations in genes involved in HR repair, especially in the TNBC subtype." (PMID 30544963, 2018). "Data from the Breast Cancer Linkage Consortium suggest the risk of epithelial ovarian cancer through age 70 years is up to 44% in BRCA1 families and is up to 27% in BRCA2 families." (PMID 29389895, 2018). "Segregation analyses studies have demonstrated that risk prediction models that allow for genes to modify effect on breast cancer risk in BRCA1 and BRCA2 mutation carriers fit significantly better to familial data than models without a modifying component." (PMID 29422015, 2018). "RB is a major target for genomic disruption in BRCA1 mutant human breast cancers, and most BRCA1-deficient BLBCs carry a dysfunctional INK4-CDK4/6-RB pathway." (PMID 29996906, 2018). "LOH is common in tumors of carriers of pathogenic BRCA1/2 germline variants that predispose to breast cancer." (PMID 29719599, 2018). "This worse outcome is analogous to reports in breast cancer studies, in which confirmed pathogenic BRCA1/2 mutations were associated with a more malignant phenotype and a worse prognosis." (PMID 29719599, 2018). "The identification of a germline BRCA1/2 mutation in a breast cancer patient is associated with potential benefits for herself as well as for her family members." (PMID 29164420, 2018). "A previous study found that the response to DDP-based drugs in breast cancer with BRCA1C61G mutation is poorer than that with homozygous BRCA1 mutation." (PMID 29950928, 2018). "BRCA1/2 mutations are somewhat less frequent in breast cancers, accounting for 5.5–6.1% of patients." (PMID 30551670, 2018). "Of 66 breast cancers in BRCA1 mutation carriers, 75.8% were triple-negative breast cancer (TNBC) and 21.2% were of the luminal type." (PMID 29176636, 2018).
breast cancer (continued). "This miRNA also proved to be a potent biomarker in the progression of basal-like breast cancer, a subtype with significant similarities to BRCA1 associated breast cancer." (PMID 30323900, 2018). "In the combined UK MARIBS and NICE studies in which 45 breast cancers were detected, only two deaths (both in BRCA1 mutation carriers) were observed at a median follow-up of 12 years." (PMID 30513626, 2018). "Previous studies demonstrated the requirement of the FA pathway and other HDR proteins, such as Rad51 and the breast cancer susceptibility proteins BRCA1 and BRCA2, for the protection of stalled forks against nascent DNA degradation." (PMID 30422114, 2018). "About 3–5% of all breast cancers and 10–15% of all ovarian cancers are associated with BRCA1 germline pathogenic variants." (PMID 29996917, 2018). "BRCA1-185-del AG mutation was found in one of the breast cancer patient who was 33 years of age at diagnosis." (PMID 30344568, 2018). "A previous study identified cancer susceptibility mutations in 11% of BRCA1/2-negative patients with early-onset breast cancer (diagnosed at <40 years of age)." (PMID 29338689, 2018). "The aim of our study is to evaluate, and for the first time, the contribution of germline mutations in BRCA1/2 to breast cancer among Jordanian patients with a selected high risk profile." (PMID 29409476, 2018). "Identification of a BRCA1 or BRCA2 mutation also alerts the woman to her increased risks of breast cancer." (PMID 29344385, 2018). "Latinas affected by breast cancer have the second highest prevalence of BRCA1/2 mutations following women of Ashkenazi Jewish ancestry." (PMID 30227649, 2018). "Statistically, approximately 5–10% of all breast cancers in women are due to mutations in BRCA1 and BRCA2 genes." (PMID 30373614, 2018). "In 2005, two landmark studies showed that PARPi selectively killed breast cancer allele 1 or breast cancer allele 2 (BRCA1/BRCA2)-deficient cancer cells by inducing the collapse of replication forks." (PMID 30680069, 2018). "The association between germline mutations of BRCA1 and hereditary form of breast cancers is well known." (PMID 28646826, 2018). "Having understood the role of CAFs on BRCA1 mutated breast cancer cells; we subsequently assessed the reciprocal effect of BRCA1 deficient cancer cells on CAFs." (PMID 30224826, 2018). "Hereditary breast cancer is well-described; around 5–10% of breast cancer patients carry high risk gene mutations like BRCA1 and BRCA2." (PMID 29409476, 2018). "The RANKL/RANK signaling pathway has also been implicated in progesterone-mediated breast tumorigenesis and BRCA1-mutated breast cancer." (PMID 30546832, 2018). "BRCA1-mutated breast cancers have been reported to show genome instability mainly due to the defect in DSB repair." (PMID 30283497, 2018). "We identified 16 qualified studies from 527 publications with 46,870 breast cancer patients including 868 BRCA1 mutations (BRCA1Mut) carriers, 739 BRCA2 mutations (BRCA2Mut) carriers, and 45,263 non-carriers." (PMID 30186165, 2018). "Breast cancer and ovarian cancer are hormone driven and are known to have some predisposition genes in common such as the two well known cancer genes BRCA1 and BRCA2." (PMID 29671401, 2018). "The data from earlier studies suggested that prophylactic oophorectomy was associated with a significant 51% (95% CI 0.37–0.65) reduction in breast cancer risk for both BRCA1 and BRCA2 mutation carriers." (PMID 30572612, 2018). "The risk of breast cancer at age 70 years in CHEK2*1100delC heterozygotes is almost as high as that for BRCA1 and BRCA2 mutation heterozygotes." (PMID 29682443, 2018). "Germline mutations in the breast cancer susceptibility gene, BRCA1, confer a high risk of developing neoplastic lesions." (PMID 30323900, 2018).
breast cancer (continued). "The cost of screening for breast cancer in patients with a germline mutation in the BRCA1/2 genes totaled R$333.75 per year." (PMID 30517521, 2018). "In the neoadjuvant setting, platinum regimens have shown a greater activity in the breast cancer arising from BRCA1/2 germline mutation." (PMID 30544963, 2018). "53BP1 deletion or mutations thus allow repair and therefore resistance in BRCA1 defective tumor cells, which is a proposed prominent resistance pathway in breast cancers." (PMID 29475976, 2018). "Our findings from the retrospective evaluation at the breast unit of PSCUH suggested that platinum-based neoadjuvant chemotherapy was highly effective in breast cancer patients with BRCA1 gene mutations." (PMID 29719582, 2018). "Risk-reducing oophorectomy in women with either BRCA1/2 mutations reduces ovarian cancer mortality and breast cancer risk." (PMID 30061853, 2018). "KDM1A overexpression has been observed in ER− breast cancers as well and was shown to correlate with a reduction in BRCA1 (a familial susceptibility gene for breast cancer) expression." (PMID 29921310, 2018). "In the most advanced stage of development in breast cancer and the combination of veliparib with carboplatin-paclitaxel or temozolomide regimen in BRCA1/2-associated advanced breast cancer was demonstrated to be feasible but efficacy was uncertain." (PMID 30544963, 2018). "In the present study, we have focused only on the BRCA1 mutations in the breast cancer cells and their effect on CAF." (PMID 30224826, 2018). "While germline BRCA1/2 (gBRCA) mutations are found in about 5% of all breast cancers, higher mutation rates are observed in TNBC patients depending on age of onset and the presence of a family history of breast and ovarian cancer." (PMID 29514593, 2018). "An example of synthetic lethality is poly (ADP-ribose) polymerase (PARP) inhibition in BRCA1/2-deficient ovarian and breast cancers." (PMID 29707125, 2018). "These evidences are in agreement with the switch toward aerobic glycolysis exhibited by BRCA1 mutated breast cancer cells." (PMID 29584711, 2018). "The prevalence of BRCA1/2 pathogenic mutations among high-risk breast cancer patients was 7.94% (35/441)." (PMID 29487695, 2018). "To test the search engine’s ability to accurately match variants from full-text disease queries, we first searched “early-onset breast cancer,” returning the expected alleles in BRCA1 and BRCA2 (4335 variants, 0.037 ± 0.020 s)." (PMID 29409527, 2018). "Among the 15 patients with bilateral or second primary breast cancer; 10 (66.7%) had deleterious or suspected deleterious BRCA1/2 mutations; 5 (33.3%) were in BRCA2 and 5 (33.3) in BRCA1." (PMID 29409476, 2018). "Other studies with retrospective follow-up of 13 to 14 years revealed a 90% reduction of breast cancer risk in women with BRCA1 and BRCA2 mutations who underwent bilateral total mastectomy." (PMID 29713580, 2018). "The onset age of breast cancer in the BRCA1 or BRCA2 mutation-positive group was significantly lower than that in the BRCA mutation-negative group (40.2 years, 41.7 years, and 45.4 years, respectively)." (PMID 29176636, 2018). "More than 20 years after the first extended family of African ancestry with a BRCA1 mutation was published, the critical genes and classes of mutations responsible for the high risk of inherited breast cancer among Nigerian women are now clear." (PMID 30130155, 2018). "More importantly, high expression of BARD1 and BRCA1 was associated with poor prognosis of ER+ breast cancer patients, especially in those received radiation therapy." (PMID 29686231, 2018).
breast cancer (continued). "In other words, risks of breast cancer to BRCA1 or BRCA2 mutation carriers is context dependent and varies by geography and the social environment in which the mutation carrier lives." (PMID 30130155, 2018). "It has been established that the breast cancer susceptibility proteins BRCA1 and BRCA2 have critical roles in HR; homozygous knockout of either of these proteins is embryonically lethal in mice." (PMID 30250272, 2018). "Indications for bilateral mastectomy were bilateral breast cancer (n=4), the presence of a BRCA1 mutation (n=1), and the presence of high risk lesions such as atypical ductal hyperplasia in the contralateral breast (n=1)." (PMID 28958980, 2018). "Inherited BRCA1/2 mutations account for an estimated 2–7% of breast cancers and 10–15% of ovarian cancers." (PMID 30103738, 2018). "In this study, we depict the crosstalk between CAFs and BRCA1 deficient breast cancer cells in vitro, which results in the transformation of CAFs to an altered phenotype of CAFs, which we named as the MAF." (PMID 30224826, 2018). "26% of MBC patients have family history of breast/ovarian cancer, 29% have personal history of cancer other than breast cancer and 14.5% are positive for BRCA1/2 mutations." (PMID 29731982, 2018). "They reported that a later age at first birth was the only probable risk factor for BRCA1-associated breast cancer, with less evidence for the role of reproductive factors for women with a BRCA2 mutation." (PMID 30572612, 2018). "Constitutive BRCA1 methylation has been found to be associated with a 3.5-fold increase in the risk of developing early-onset breast cancer and a major predisposition factor for serous ovarian cancer." (PMID 30049288, 2018). "The Bahamas has the highest known prevalence of BRCA mutations among breast cancer patients of any country; 23% of women with breast cancer in the Bahamas were found to carry one of seven founder mutations in the BRCA1 or BRCA2 gene." (PMID 29266833, 2018). "Retrospective follow-up in two patients revealed a positive family history for breast cancer and consecutive germline mutation testing confirmed presence of BRCA1 mutations." (PMID 29453630, 2018). "Women who inherit a deleterious germline BRCA1 or BRCA2 mutation face high lifetime risks of developing breast cancer by age 80, which are estimated at 72% and 69%, respectively." (PMID 30572612, 2018). "BRCA1 gene analysis was also performed in 121 Moroccan women diagnosed with breast cancer; 31.6% (6/19) of familial and 1% (1/102) of early-onset sporadic cases (< 45 years) were found to be associated with BRCA1 mutations." (PMID 29409476, 2018). "For example, array-based approaches have been used to define a genomic signature of HR deficiency and identified significant changes in copy number profiles between BRCA1/2-mutated tumors and those that were wild type in breast cancer." (PMID 30120226, 2018). "In a BRCA1-deficient breast cancer mouse model, the combination of a PARP inhibitor with cisplatin or carboplatin increases the recurrence-free and overall survival, indicating that PARP inhibitors can improve the efficacy of DNA-damaging compounds." (PMID 30234015, 2018). "Despite its genetic wealth, few breast cancer genetic studies have been performed in the TUN population such as those that focused on the identification of the mutational spectrum of BRCA1 and BRCA2." (PMID 30594178, 2018).
breast cancer (continued). "MiR-155 is up-regulated only in breast cancer cells with loss of wild-type BRCA1 or mutant-BRCA1, since HDCA2 cannot be recruited on the miR promoter." (PMID 29401683, 2018). "The breast cancer risk in a BRCA1 mutation carrier and the possible interference of hyperprolactinemia and life events were also discussed." (PMID 30518416, 2018). "Between 5 and 7% of the breast cancer cases are due to hereditary factors, and 25% of these are down to genetic mutations in BRCA1 and BRCA2 genes." (PMID 30061853, 2018). "Data for the 5,949 first-degree relatives was utilized to obtain estimates of breast cancer penetrance in mutation carriers (230 from BRCA1 carrier relatives, 309 from BRCA2 carrier relatives and 5,410 from non-carrier relatives)." (PMID 29861850, 2018). "BRCA1/2 mutations are the strongest known breast cancer risk factors, conferring up to a 60–80% lifetime risk of breast cancer among female carriers." (PMID 30103738, 2018). "For the studies of BRCA1-associated breast cancer, we generated the female Brca1 conditional knockout mice with MMTV-cre-mediated recombination (Brca1co/coMMTV-cre)." (PMID 30652068, 2018). "Even if mutations in BRCA1 give the higher susceptibility to develop breast cancer, several data suggest that this predisposition is dependent on a combination of several low penetrance factors." (PMID 30283497, 2018). "Kuchenbaecker, in a recent study, showed that the BRCA1 risk of breast cancer was estimated at 72% and BRCA2 at 69%." (PMID 30340058, 2018). "Germline mutations in either the BRCA1 or BRCA2 (BRCA1/2) gene account for approximately 2–3% of all breast cancer, but around 30% of hereditary breast cancer." (PMID 30544963, 2018). "Depletion of BRCA1 protein in mouse mammary glands results in defects in lactational development and increased susceptibility to mammary cancer." (PMID 30323900, 2018). "Women who inherit a deleterious BRCA1 or BRCA2 mutation face substantially increased risks of developing breast cancer, which is estimated at 70%." (PMID 30572612, 2018). "Although carriers of BRCA1 germline mutations have an 80% lifetime risk of breast cancer, such cases make a small contribution to breast cancer in the general population." (PMID 30590041, 2018). "Several studies indicated that miR-342 is linked to BRCA1 mutated breast cancer, most of which are the Basal subtype." (PMID 30180792, 2018). "While being initially essentially confined to the field of screening and/or prevention, the knowledge of a BRCA1/2 germline mutation has now become a major biomarker for therapeutic decision in advanced breast cancer management." (PMID 30544963, 2018). "Collectively, our data demonstrate genome-wide transcriptional regulation by BRCA1 and suggest target genes as biomarker candidates for BRCA1-associated breast cancer." (PMID 29757984, 2018). "BRCA1 mutation carriers have a significant lifetime risk of breast cancer, with their primary risk-reduction option being bilateral mastectomy." (PMID 30580266, 2018). "The present study demonstrates a clear protective effect of early first pregnancy on breast cancer risk in both BRCA1 and BRCA2 mutation carriers." (PMID 29116468, 2018). "The ability to distinguish vinblastine responders from non-responders would be helpful for maximizing the therapeutic benefit of vinblastine therapy in BRCA1-associated breast cancer." (PMID 30327455, 2018). "By the age of 70, women carrying germline mutations in BRCA1 have a 60% average cumulative risk for breast cancer and a 59% risk for ovarian cancer." (PMID 29996917, 2018). "For single-gene loci, hypermethylation of CDKN2A in colorectal cancer, MGMT in glioblastoma, BRCA1 in breast cancer were reported to be associated with poor clinical outcomes." (PMID 30217224, 2018).